STAT3 (signal transducer and activator of transcription 3)
Diseases named in the same sentence as STAT3 in open-access papers (continued):
Sharing a sentence is not in itself a finding about the gene and the disease.
viral myocarditis (9 papers, 2012 to 2025). Myocarditis that is caused by an infection with a viral agent. "Andrographolide may improve viral myocarditis by inhibiting the increase in serum TNF-α, hs-CRP and cTnI levels caused by viral myocarditis, activating the IL-10/STAT3 anti-inflammatory pathway, and inhibiting the PI3K/AKT/NF-κB pathway." (PMID 36238575, 2022). "Since activated STAT3 may play a protective role in viral myocarditis, the effect of activated STAT3 on cardiomyocyte damage caused by CVB3 infection was evaluated through LDH assay." (PMID 33658937, 2020). "Given that cell apoptosis is one of the mechanisms in viral myocarditis and one of the important manifestations in myocardial damage, we tested the impact of activated STAT3 in the regulation of cardiomyocyte apoptosis." (PMID 33658937, 2020). "Upon phosphorylation, activated STAT3 plays a role in heart remodeling of myocardial infarction and the progression of dilated cardiomyopathy, as well as in viral myocarditis." (PMID 33658937, 2020). "For this purpose, we injected STAT3 inhibitor AG490 into the abdominal cavity of mice with viral myocarditis." (PMID 33658937, 2020). "To further determine the effect of STAT3 in viral myocarditis, we constructed Lv-STAT3 and Lv-sh-STAT3 to regulate the level of p-STAT3 in NMCs." (PMID 33658937, 2020). "In viral myocarditis, STAT3 opposes the initiation of the dilated phenotype by maintaining membrane integrity via the expression of dystrophin." (PMID 30619368, 2018). "We also inferred that in mice with viral myocarditis, methyllycaconitine blocked α7nAchR, decreasing the phosphorylation of STAT3; this resulted in the up-regulation of the expression of the cytokines TNF-α and IL-6 and aggravated the inflammatory response." (PMID 25396421, 2014). "Here, we demonstrate for the first time that STAT3 deletion also leads to an aggravated cardiac function in viral myocarditis induced by CVB3." (PMID 22675647, 2012). "Here, we study the effect of cardiomyocyte-restricted knockout of STAT3 in viral myocarditis to evaluate its role during inflammation as well as adverse cardiac remodelling in experimental viral myocarditis." (PMID 22675647, 2012). "Next, we tried to clarify what role STAT3 played in viral myocarditis." (PMID 33658937, 2020). "This synchronized change suggests that survivin may be a downstream target protein of STAT3 in viral myocarditis." (PMID 33658937, 2020). "Nevertheless, whether STAT3 inhibits apoptosis in viral myocarditis through survivin requires more in-depth research." (PMID 33658937, 2020). "Herein we aimed to explore the potential role and mechanism of STAT3 in viral myocarditis." (PMID 33658937, 2020). "Interestingly, in the present study, we obtained novel findings to the effect that the expression of survivin was synchronized with that of STAT3 in a time-dependent manner in the context of viral myocarditis." (PMID 33658937, 2020). "Thus, we inferred that in mice with viral myocarditis, nicotine activated α7nAchR, increasing the phosphorylation STAT3; this resulted in the down-regulation of the expression of the cytokines TNF-α and IL-6 and relieved the inflammatory response." (PMID 25396421, 2014). "While its role in acute viral myocarditis is still unknown, it is interesting that the signalling via the gp130/STAT3 pathway is profoundly altered in the myocardium of patients with DCM." (PMID 22675647, 2012). "Therefore, STAT3 seems to be a crucial factor for the resolution of viral myocarditis." (PMID 22675647, 2012). "We also conclude that blocking α7nAchR reduces the phosphorylation of STAT3, increases the expression of TNF-α and IL-6, aggravating viral myocarditis." (PMID 25396421, 2014). "In acute viral myocarditis, activation of α7nAchR increases the phosphorylation of STAT3, reduces the levels of TNF-α and IL-6, and, ultimately, alleviates viral myocarditis." (PMID 25396421, 2014).
viral myocarditis (continued). "Because nicotine is a α7nAchR agonist and methyllycaconitine is a α7nAchR antagonist, we conclude that α7nAchR activation increases the phosphorylation of STAT3, reduces the expression of TNF-α and IL-6, and, ultimately, alleviates viral myocarditis." (PMID 25396421, 2014). "They found that α7 nAChR activation increases STAT3 phosphorylation, decreases TNF-α and IL-6 expressions, and ultimately reduces viral myocarditis, indicating that α7 nAChR agonists could be a promising new strategy for patients with viral myocarditis." (PMID 33425684, 2021). "Moreover, the inhibition of α7nAchR reduces the phosphorylation of STAT3, increases the levels of TNF-α and IL-6, and, ultimately, aggravates viral myocarditis." (PMID 25396421, 2014). "We used STAT3-deficent mice with a cardiomyocyte-restricted knockout and induced a viral myocarditis using Coxsackievirus B3 (CVB3) which induced a severe inflammation during the acute phase of the viral myocarditis." (PMID 22675647, 2012). "We show for the first time that STAT3 KO induces adverse cardiac remodelling leading to DCM in the subacute phase of viral myocarditis, while no change was seen in the acute phase when cardiomyocyte-restricted STAT3 KO was compared to wild-type." (PMID 22675647, 2012).
AIDS (8 papers, 2007 to 2025). A syndrome resulting from the acquired deficiency of cellular immunity caused by the human immunodeficiency virus (HIV). "Conversely, our data suggests that miRs could indirectly act on key regulators of STAT3/IL-6 axis ultimately contributing to the chronic immune activation observed in AIDS." (PMID 26116514, 2015). "Thus STAT3 activation in the Nef-expressing cells is important for the interpretation of the role played by the Nef protein in AIDS pathogenesis." (PMID 23554973, 2013). "Finally, studies were performed to determine whether IL-6 acts on human AIDS-NHL cells by STAT3 stimulation as it does in LCL8664." (PMID 17324269, 2007). "With EBV+ AIDS-DLBCL patients continuing to face poorer outcomes compared to EBV- AIDS-DLBCL patients despite antiretroviral therapy and advanced chemotherapeutic regimens, targeting ZC3H18 alongside EBNA1 (or STAT3) may offer greater benefit." (PMID 40354417, 2025).
anaplastic thyroid cancer (8 papers, 2014 to 2026). "Phosphorylation of Tyr-705 of STAT3 is induced by leptin and OB3 in anaplastic thyroid cancer cells." (PMID 28750624, 2017). "When anaplastic thyroid cancer cells were treated with leptin in the presence or absence of specific signal transduction pathway inhibitors PD98059, LY294002 and an inhibitor of STAT3, S31-201, the leptin-induced cell invasion was inhibited by PD and S31-201, but not LY294002." (PMID 27050378, 2016). "Intriguingly, in the human anaplastic thyroid cancer line ARO, STAT3 could directly interact with ectopically expressed RET/PTC1 and phosphorylation of its Tyr705 did not require either JAK or c-Src kinase, indicating a possibility of direct STAT3 activation by the oncogenic kinase." (PMID 24662939, 2014). "In addition, phosphorylation of Tyr-705 in STAT3, but not Ser-727, was induced by leptin and OB3 in anaplastic thyroid cancer cells." (PMID 27050378, 2016). "Indeed, pharmacologic inhibition of ERK1/2 and STAT3, but not PI3K, signaling inhibited leptin-induced invasion in anaplastic thyroid cancer cells." (PMID 27050378, 2016).
aspergillosis (8 papers, 2020 to 2025). Aspergillosis is an infection, growth, or allergic response caused by the Aspergillus fungus. "Francois Danion and colleagues proved that STAT3-deficient patients with aspergillosis were associated with a defective adaptive immune response against A. fumigatus infection and produced lower levels of cytokines, including IFN-γ, IL-17, and IL-22178." (PMID 35504997, 2022). "Association of IFN-γ with antifungal treatment and surgery limits the specific evaluation of IFN-γ therapy but confirms the urgent need of further studies on IFN-γ therapy in the STAT3-deficient patients with aspergillosis." (PMID 32047500, 2020). "STAT3-deficient patients showed an increased susceptibility to pulmonary aspergillosis, especially when they had preexisting lung cavities." (PMID 32047500, 2020). "This warrants innovative immunotherapeutic approaches, based on cytokine, to treat STAT3-deficient patients with severe chronic forms of pulmonary aspergillosis." (PMID 32047500, 2020). "Among the STAT3-deficient patients, those with aspergillosis showed further lower secretion of IFN-γ upon stimulation of their PBMCs with A. fumigatus conidia compared to the patients without aspergillosis." (PMID 32047500, 2020). "The combination of three positive criteria (total IgE > 1,000 kU/L, specific anti-Aspergillus IgE ≥ 0.1 and specific anti-Aspergillus IgG above the cut-off) was associated with aspergillosis in the STAT3-deficient population." (PMID 32047500, 2020). "Future studies with more significant numbers of additional animals and various degrees of immunosuppression may be required to decipher the exact role of STAT3 deficiency in CD4+ T cells in susceptibility to aspergillosis in immunosuppressed mice." (PMID 33526558, 2021). "The presence of lung cavities in association with defective adaptive immune responses, defective production of antimicrobial peptides and chemokine might partially explain the development of pulmonary aspergillosis during STAT3-deficiency." (PMID 32047500, 2020). "Additionally, there were no patients with Aspergillus infections, in contrast to the 17.5% of STAT3-deficient patients reported to experience aspergillosis in the lung cavities." (PMID 32944025, 2020). "However, the immunological defects associated with aspergillosis in STAT3-deficient patients remain unknown." (PMID 32047500, 2020). "In a retrospective French study on STAT3-HIES patients with pulmonary Aspergillosis, six patients underwent seven episodes of surgery." (PMID 37741967, 2023). "In the French STAT3-deficient cohort, we identified three patients treated with combination of IFN-γ and antifungals for four episodes of aspergillosis, and two of them showed favorable outcome." (PMID 32047500, 2020). "Extrapulmonary aspergillosis is reported, however, in association with STAT3 haploinsufficiency that did not appear to impact antifungal Th17 responses." (PMID 32185141, 2020). "STAT3-deficient patients with ongoing aspergillosis had higher specific anti-Aspergillus IgE and IgG titers compared to those without aspergillosis." (PMID 32047500, 2020). "Eleven of them had developed aspergillosis (STAT3-asp: six with chronic pulmonary aspergillosis (CPA), three allergic bronchopulmonary aspergillosis (ABPA), and two had both ABPA-CPA; eight were with ongoing aspergillosis and three in complete remission at the time of our study)." (PMID 32047500, 2020). "Five (62.5%) STAT3-deficient patients with ongoing aspergillosis had these three positive tests compared to none in the STAT3-deficient patients without or with prior aspergillosis (p < 0.01)." (PMID 32047500, 2020). "Moreover, we compared anti-conidial responses of PBMCs isolated from STAT3-deficient patients with and without existing aspergillosis." (PMID 32047500, 2020). "It is not clear whether STAT3 deficiency alone is sufficient to predispose patients to aspergillosis." (PMID 32185141, 2020).
aspergillosis (continued). "Moreover, those STAT3-deficient patients who developed aspergillosis showed further lower level of IFN-γ than the STAT3-deficient patients without aspergillosis." (PMID 32047500, 2020). "No statistical difference in terms of age, sex, or immunophenotyping was evidenced between the six patients who developed aspergillosis (STAT3-asp) and those who did not (STAT3-w/o-asp)." (PMID 32047500, 2020).
autism (8 papers, 2016 to 2024). Persistent deficits in social interaction and communication and interaction as well as a markedly restricted repertoire of activity and interest as well as repetitive patterns of behavior. "Activation of JAK2 in cases of autism induces phosphorylation of STAT3 in the astrocytes and microglia which in turn elicits profound damage to the neural tissues." (PMID 39596986, 2024). "S3I-201 and flavonoids have previously been shown to target STAT3 in a model of autism, thereby improving the disease." (PMID 35164154, 2022). "An increased level of signal transducer and activator of transcription 3 (STAT3) and a decreased level of peroxisome proliferator-activated receptor (PPAR) gamma have been linked to autism pathogenesis." (PMID 35164154, 2022). "Accumulating data suggested that Janus kinase 2 (JAK2)/signal transducer and activator of transcription-3 (STAT 3)/peroxisome proliferator-activated receptor (PPAR) gamma signaling pathway might play a pivotal role in the pathogenesis of autism." (PMID 39596986, 2024). "As such, a specific alteration of T clones in PBMCs of autism patients versus typically developing children had already been observed in previous studies: a reduction in Foxp3 (T reg) and an increase in STAT3 and ROR γ t (Th17), T-bet (Th1) and GATA-3 (Th2) were noted." (PMID 37588589, 2023). "Additionally, diosmin and luteolin have been used as STAT3 inhibitors to treat autism." (PMID 35164154, 2022). "Upon activation by the proinflammatory cytokines released in cases with autism, JAK2 receptors were proven to enhance STAT3 phosphorylation in the astrocytes and microglia." (PMID 39596986, 2024). "Aside from that, we can state that assessing STAT3 and PPAR-gamma levels can be a viable biomarker for autism diagnosis due to their participation in disease development and severity." (PMID 35164154, 2022). "The level of STAT3 was found to be significantly higher in the brain homogenate and CSF of autistic rats treated with a PPA-induced experimental model of autism in adult rats." (PMID 35164154, 2022). "The levels of STAT3 and PPAR gamma in both brain homogenate and CSF were measured to confirm the involvement of signalling processes in the pathology of autism." (PMID 35164154, 2022).
autoimmune uveitis (8 papers, 2013 to 2025). An autoimmune form of uveitis (disease). "The deletion of STAT3 in mouse B cells resulted in exacerbated experimental autoimmune uveitis, reduced murine IL-10+ and IL-35+ Breg frequency and reduced Treg expansion." (PMID 35660734, 2022). "A previous study reported that miR-155 could directly bind to STAT3 in autoimmune uveitis mice model, and the expression of mature miR-155 was defective in the absence of STAT3." (PMID 38951930, 2024). "We also examined the effect of STAT3 in CD8+ T cell functions in vivo, specifically in host immunity to HSV-1 infection and autoimmune uveitis." (PMID 24204098, 2013).
bladder urothelial carcinoma (8 papers, 2016 to 2025). "AG490 is a Jak2/STAT3 inhibitor, which can activate DCs by inducing cancer cell death, and suppress progression of bladder transitional cell carcinomas." (PMID 27556503, 2016). "Moreover, the Signal Transducer and Activator of Transcription 3 (STAT3) targeted by IL-6 has been found to be highly activated in infiltrating basal-type urothelial bladder cancer tissue compared to luminal UBC." (PMID 38339010, 2024). "Activated STAT3 signaling is related to bladder transitional cell carcinomas growth and survival." (PMID 27556503, 2016). "For example, FOXQ1 expression inhibited activation of the IL6/JAK/STAT3 signaling pathway, IL2/STAT5 signaling pathway, allograft rejection pathway, apical junction pathway, and complement pathway in bladder urothelial carcinoma." (PMID 36118871, 2022). "In a bladder urothelial carcinoma model, CEBPD expression is upregulated by STAT3 activation and promotes cancer drug resistance." (PMID 31300060, 2019).
breast adenocarcinoma (8 papers, 2014 to 2021). "Using the comprehensive Kaplan-Meier survival analysis platform, we discovered that decreased mRNA expression of STAT3 is an unfavorable prognostic factor of overall survival for patients with breast adenocarcinoma." (PMID 29423040, 2018). "Introduction of an active Src was seen to induce HGF expression with concomitant STAT3 activation in murine mammary adenocarcinoma cells." (PMID 24743777, 2014). "In accordance with STAT3's pro-cancerous properties, constitutive tyrosine phosphorylation of STAT3 is observed in nearly a third of breast adenocarcinomas and is an indicator of poor prognosis." (PMID 25153725, 2014). "In mammary adenocarcinoma cells, SIN3A interacts with STAT3 to silence tumor suppressor gene and inhibit cell survival." (PMID 35127514, 2021). "Next, we used T47D cells, a human breast adenocarcinoma cell line which lacks constitutively active Stat but is biologically responsive to GH and IL6 which are activators of Stat5 and Stat3 signaling pathway, respectively." (PMID 27557509, 2017). "Our lab observed increased STAT1 expression in human mammary adenocarcinoma in the presence of nuclear EGFR, which synergized with co-expression of STAT3 to further enhance STAT1 levels." (PMID 24743777, 2014). "To analyze whether NPQ-C6 was also able to downregulate cytokine-induced STAT5/3 activities, we used a human breast adenocarcinoma cell line (T47D) which fails constitutively active STAT but is able to respond to GH and IL6, which are activators of STAT5 and STAT3 signaling pathway, respectively." (PMID 30687103, 2018).
chronic pancreatitis (8 papers, 2012 to 2025). A chronic inflammatory process causing damage and fibrosis of the pancreatic parenchyma. "Signal transducer and activator of transcription 3 (Stat3) has been recognized as a indispensable modulator of pancreatic β-cell development and function, and has been implicated in regulating β-cell cycle and protecting β-cells from DNA damage in chronic pancreatitis." (PMID 37903776, 2023). "We also demonstrate that the protective role of miR-301a deletion in chronic pancreatitis and PanIN is dependent on two downstream axes: Tsc1/mTOR and Gadd45g/Stat3." (PMID 35211358, 2022). "We previously demonstrated that Reg3g promoted pancreatic carcinogenesis via a STAT3 signaling pathway in a murine model of chronic pancreatitis." (PMID 28880262, 2017). "In cerulein-induced tissue of chronic pancreatitis, IHC staining of p-STAT3 was dramatically increased." (PMID 28738823, 2017). "Accordingly, we showed expression of p-STAT3 in precursor lesions from KC mice, and chronic pancreatitis induced an increased STAT3 activity." (PMID 28738823, 2017). "Accordingly, the activity of STAT3 signaling was decreased in KC mice as well as mice with chronic pancreatitis following metformin treatment." (PMID 28738823, 2017). "Treatment with metformin reduced the activation of STAT3 signaling in KC mice and mice with chronic pancreatitis." (PMID 28738823, 2017). "Recent studies in mice have demonstrated that PDAC induction is dependent upon both the k-ras oncogene and a STAT3-dependent inflammatory component, such as chronic pancreatitis." (PMID 22291919, 2012). "Given the robust effect of miR-301a in activating NF-κB and Stat3 in the tumor microenvironment, we expected that deletion of miR-301a would lead to a reduction of expression of inflammatory cytokines in caerulein-induced chronic pancreatitis in mice." (PMID 35211358, 2022). "Of note, aberrant regulation of Gadd45g/Stat3 was only found to accelerate PanIN formation but not chronic pancreatitis in mice ablated of miR-301a." (PMID 35211358, 2022).